AURKB (aurora kinase B)
Description:
Serine/threonine-protein kinase component of the chromosomal passenger complex (CPC), a complex that acts as a key regulator of mitosis. The CPC complex has essential functions at the centromere in ensuring correct chromosome alignment and segregation and is required for chromatin-induced microtubule stabilization and spindle assembly. Involved in the bipolar attachment of spindle microtubules to kinetochores and is a key regulator for the onset of cytokinesis during mitosis. Required for central/midzone spindle assembly and cleavage furrow formation. Key component of the cytokinesis checkpoint, a process required to delay abscission to prevent both premature resolution of intercellular chromosome bridges and accumulation of DNA damage: phosphorylates CHMP4C, leading to retain abscission-competent VPS4 (VPS4A and/or VPS4B) at the midbody ring until abscission checkpoint signaling is terminated at late cytokinesis. AURKB phosphorylates the CPC complex subunits BIRC5/survivin, CDCA8/borealin and INCENP. Phosphorylation of INCENP leads to increased AURKB activity. Other known AURKB substrates involved in centromeric functions and mitosis are CENPA, DES/desmin, GPAF, KIF2C, NSUN2, RACGAP1, SEPTIN1, VIM/vimentin, HASPIN, and histones H1.4 and H3. A positive feedback loop involving HASPIN and AURKB contributes to localization of CPC to centromeres. Phosphorylation of VIM controls vimentin filament segregation in cytokinetic process, whereas histone H3 is phosphorylated at 'Ser-10' and 'Ser-28' during mitosis (H3S10ph and H3S28ph, respectively). AURKB is also required for kinetochore localization of BUB1 and SGO1. Key regulator of active promoters in resting B- and T-lymphocytes: acts by mediating phosphorylation of H3S28ph at active promoters in resting B-cells, inhibiting RNF2/RING1B-mediated ubiquitination of histone H2A and enhancing binding and activity of the USP16 deubiquitinase at transcribed genes (By similarity). Acts as an inhibitor of CGAS during mitosis: catalyzes phosphorylation of the N-terminus of CGAS during the G2-M transition, blocking CGAS liquid phase separation and activation, and thereby preventing CGAS-induced autoimmunity. Phosphorylates KRT5 during anaphase and telophase (By similarity). Phosphorylates ATXN10 which promotes phosphorylation of ATXN10 by PLK1 and may play a role in the regulation of cytokinesis and stimulating the proteasomal degradation of ATXN10.
Synonyms: AIM-1; ARK-2; AIK2; AIM1; ARK2; STK12; STK5; IPL1; AurB; PPP1R48; STK-1; aurkb-sv1; aurkb-sv2
Tractability: Small molecule: a drug acting on it is in phase 2 or 3 trials; a structure with a bound ligand is known; a high-quality ligand is known; it belongs to a druggable protein family. PROTAC: it is named in the literature on targeted protein degradation; UniProt records ubiquitination sites on it; ubiquitination databases record sites on it; a small molecule that binds it is known.
Target class: Other protein kinase AUR family; Other protein kinase group; Enzyme; Kinase; Protein Kinase
Chemical probes: AMG-900 (high quality), Aurora-compound 1 (high quality), BI 831266 (high quality), CHEMBL1243200, DANUSERTIB, FMF-01-086-2 (high quality), FMF-03-145-1 (high quality), FMF-04-159-2 (high quality), PD080849, PD080877, PD080889, PD080895, PD080919, PD080957, PD080995, PD081029, PD081071, PD081085, PD081091, PD081139, and 67 more
Safety:
Unwanted effects reported when the protein is acted on. In parentheses: how it was acted on, where the effect was seen, and who reports it.
Mutagenic effect (inhibition; genetic toxicity; source: Brennan et al. (2024))
neutropenia (inhibition; blood; source: Brennan et al. (2024))
heart disease (cardiovascular system; source: Force et al. (2011))
Gene: Protein-coding gene on chromosome 17 (8,204,335 to 8,210,634, reverse strand). Ensembl gene ENSG00000178999.
Subcellular location: Nucleus; Chromosome; Chromosome, centromere; Chromosome, centromere, kinetochore; Cytoplasm, cytoskeleton, spindle; Midbody
Subcellular location (Human Protein Atlas): Nucleoplasm; Kinetochore; Midbody
Pathways (Reactome):
Cell Cycle: APC/C:Cdh1 mediated degradation of Cdc20 and other APC/C:Cdh1 targeted proteins in late mitosis/early G1; Amplification of signal from unattached kinetochores via a MAD2 inhibitory signal; EML4 and NUDC in mitotic spindle formation; Mitotic Prometaphase; Resolution of Sister Chromatid Cohesion; Separation of Sister Chromatids
Metabolism of proteins: SUMOylation of DNA replication proteins
Signal Transduction: RHO GTPases Activate Formins
Gene Ontology:
Molecular function: histone H1-4S27 kinase activity; kinase binding; protein binding; protein serine kinase activity; protein serine/threonine kinase activity; protein serine/threonine/tyrosine kinase activity; ATP binding; protein kinase activity
Biological process: cell cycle G2/M phase transition; cellular response to UV; cleavage furrow formation; mitotic sister chromatid biorientation; mitotic spindle midzone assembly; negative regulation of B cell apoptotic process; negative regulation of cGAS/STING signaling pathway; negative regulation of protein localization to chromatin; negative regulation of transcription by RNA polymerase II; positive regulation of cytokinesis; positive regulation of lateral attachment of mitotic spindle microtubules to kinetochore; positive regulation of microtubule depolymerization; positive regulation of mitotic sister chromatid segregation; positive regulation of telomere maintenance; protein localization to kinetochore; repair of mitotic kinetochore microtubule attachment defect; spindle organization; midbody abscission; mitotic cell cycle; mitotic cytokinesis; mitotic cytokinesis checkpoint signaling; mitotic spindle assembly; mitotic spindle organization; negative regulation of cytokinesis; positive regulation of attachment of mitotic spindle microtubules to kinetochore; and 10 more
Cellular component: chromatin; chromosome; chromosome passenger complex; condensed chromosome, centromeric region; kinetochore; microtubule cytoskeleton; midbody; nucleoplasm; nucleus; centrosome; cytosol; spindle; spindle microtubule; spindle midzone; spindle pole; chromocenter; chromosome, centromeric region; mitotic spindle midzone; mitotic spindle pole
Genetic constraint (gnomAD): Loss-of-function variants: 29 observed, 41.31 expected, observed/expected ratio (o/e) 0.7, 90% interval 0.52 to 0.96. The upper end of that interval is the gene's LOEUF score, 0.96, which puts it in group 4 of 6, group 1 being the genes least tolerant of losing a copy. Missense variants: 383 observed, 468.08 expected, observed/expected ratio (o/e) 0.82, 90% interval 0.75 to 0.89. Synonymous variants: 175 observed, 182.73 expected, observed/expected ratio (o/e) 0.96, 90% interval 0.85 to 1.09.
Homologues: Orthologues: chimpanzee AURKB (98% identical), macaque AURKB (98% identical), dog AURKB (92% identical), rabbit AURKB (90% identical), pig AURKB (90% identical), guinea pig AURKB (86% identical), mouse Aurkb (84% identical), rat Aurkb (84% identical), tropical clawed frog aurkb (69% identical), zebrafish aurkb (65% identical), Caenorhabditis elegans air-2 (51% identical). Paralogues in human: AURKC (69% identical), AURKA (61% identical).
Diseases named in the same sentence as AURKB in open-access papers:
AURKB is named in the same sentence as 186 diseases in open-access papers, as found by Europe PMC text mining. Sharing a sentence is not in itself a finding about the gene and the disease. The quoted sentences say what the papers report.
breast cancer (73 papers, 2011 to 2025). A primary or metastatic malignant neoplasm involving the breast. "Dysregulation of AURKB, often characterized by its overexpression, has been implicated in various malignancies, including breast cancer." (PMID 40710353, 2025). "Collectively, these results suggest that the phosphorylation level of AURKB in breast cancer cells has a strong association with resistance to PTX." (PMID 35088239, 2022). "It has been recognized that the phosphorylation level of AURKB is associated with resistance to PTX in breast cancer cells." (PMID 35088239, 2022). "Studies show the association of AURKB overexpression with cisplatin resistance in gastric cancer cells, tamoxifen resistance in breast cancer and cetuximab resistance in head and neck squamous cell carcinoma." (PMID 35810383, 2022). "Further, loss-of-function RNAi screen identified that AURKB inhibition along with rapamycin had a synergistic activity in breast cancer cell lines." (PMID 33915740, 2021). "Based on our in vitro studies with the antiestrogen resistant T47D breast cancer cell lines, analysis of the association between Aurora kinase B and survival of breast cancer patients treated with fulvestrant would also be of great interest." (PMID 25885472, 2015). "In breast cancer, AURKB expression is markedly upregulated and correlates with increased tumor cell proliferation and resistance to therapy." (PMID 40710353, 2025). "Expression analysis via quantitative PCR confirmed that let-7b-5p was downregulated and AURKB was upregulated in breast cancer tissue samples." (PMID 39787178, 2025). "We further measured the IC50 of PTX in a panel of basal‐like and luminal breast cancer cell lines, for which AURKB mRNA expression levels were obtained from the dataset on Gene Expression‐Based Outcome for Breast Cancer Online (GOBO)." (PMID 40099930, 2025). "It has been demonstrated that AURKB stimulates epithelial-mesenchymal transition by stabilizing Snail1, resulting in basal-like breast cancer metastases." (PMID 39787178, 2025). "Although AURKB inhibition has shown therapeutic potential in combination regimens for breast cancer, the emergence of resistance remains a significant clinical challenge." (PMID 40710353, 2025). "Together, these finding demonstrated that MOF regulates breast cancer cell proliferation and tumor growth via AURKB K215 acetylation and raises the possibility of a broader oncogenic role for this epigenetic axis, warranting further investigation." (PMID 40710353, 2025). "In this context, our findings underscore the importance of combined inhibition strategies involving AURKB and highlight its critical role in drug-resistant breast cancer." (PMID 40710353, 2025). "Recent studies have evaluated how dysregulation in AURKB leads to increased phosphorylation of Survivin (an inhibitor of apoptosis) and its correlation with a worse prognosis in breast cancer." (PMID 38886738, 2024). "Aurora B expression is elevated in breast cancer due to cell proliferation, and co‐deletion of AURKB at 17p13 suggests an integrated system that helps cell clones with impaired mitotic kinase function survive." (PMID 38717954, 2024). "AURKB promoted the metastasis of basal-like breast cancer by stabilizing Snail1 to induce epithelial-mesenchymal transition." (PMID 38713155, 2024). "Currently, research is being done on AURKB as a potential therapeutic target for several tumour types, including leukemia, prostate cancer (PC), gastric cancer (GC), breast cancer, and non-small cell lung cancer (NSCLC)." (PMID 39014265, 2024). "AURKB expression is found to be aberrantly elevated in multiple types of cancers, such as breast cancer, prostate cancer, and lung cancer, indicating its possible potential as an oncogene." (PMID 38713155, 2024). "For instance, while AURKB was identified as one of the hub genes in Basal-like breast cancer, AURKA was recognized as a critical gene in HER2-enriched breast cancer." (PMID 37231064, 2023).
breast cancer (continued). "More interestingly, AURKB played a driver role in facilitating the transformation of murine epithelia into the mammary tumor by inducing polyploid and consequent genomic instability." (PMID 37079315, 2023). "It has been reported that in several lung cancer and breast cancer cell lines, loss of RB1 makes cells hyperdependent on AURKB for their survival." (PMID 35853811, 2022). "We then identified six hub genes (PSMC6, AURKB, CASP9, BAD, ZNF24, and SSX2IP) that were significantly associated with the prognosis of breast cancer." (PMID 36199443, 2022). "Collectively, this study provides experimental evidence for PRKCE/AURKB/RAB27B axis in regulating the resistance to paclitaxel (PTX) in breast cancer cells, offering a potential intervention target for reversing drug resistance." (PMID 35088239, 2022). "AURKB was found to be correlated with the cell proliferation and AURKB expression is an independent prognostic index of breast cancer, especially for triple negative breast cancer (TNBC)." (PMID 36199443, 2022). "Six hub genes (PSMC6, AURKB, CASP9, BAD, ZNF24, and SSX2IP) that were significantly associated with the prognosis of breast cancer." (PMID 36199443, 2022). "For instance, TTK (MPS1), a dual‐specificity kinase that assists AURKB in chromosome alignment during mitosis and promotes aneuploidy in breast cancer." (PMID 34967509, 2022). "Then, detection of the collected clinical specimens by quantitative PCR showed that the relative content of AURKB mRNA in breast cancer tissues was significantly higher than that in the corresponding adjacent tissues." (PMID 35088239, 2022). "In summary, considering the difference in the phosphorylation level of AURKB between breast cancer cells and wild-type cells, our study confirms the positive correlation between AURKB phosphorylation and drug resistance via both cell and animal experiments." (PMID 35088239, 2022). "In our subsequent experiment, it was observed that there was a significant difference in the subcellular localization of AURKB in wild-type breast cancer cells (MDA-MB-231 and BT549) and the corresponding PTX-resistant cells." (PMID 35088239, 2022). "Breast cancer cells resistant to the drug fulvestrant showed increased AURKB phosphorylation and AURKB inhibitor barasertib preferentially reduced growth of tumor cells resistant to fulvestrant and tamoxifen." (PMID 33915740, 2021). "These aromatase resistant breast cancer cells also showed significant growth inhibition when treated with barasertib (specific to AURKB) and JNJ-7706621 (AURKA/B and CDK inhibitor)." (PMID 33915740, 2021). "The most correlated mRNA with AURKB was FAM64A, which is a marker of cell proliferation, and has been found to be associated with the aggressive growth of pancreatic cancer and breast cancer." (PMID 33612479, 2021). "Meanwhile, AURKB also over-expresses in colorectal cancer, liver cancer, and breast cancer according to the data from TCGA in this study." (PMID 32194417, 2020). "Consistently, AURKB overexpression also induces the tamoxifen resistance and poor prognosis in breast cancer." (PMID 28147341, 2017). "Aurora kinase B expression was confined to the nucleus of breast cancer cells and scored as percentage positive tumor cells." (PMID 25885472, 2015). "The selective Aurora kinase B inhibitor barasertib was identified to preferentially inhibit growth of fulvestrant resistant T47D breast cancer cell lines." (PMID 25885472, 2015). "Our results indicate that Aurora kinase B is a driving factor for growth of antiestrogen resistant T47D breast cancer cell lines, and a biomarker for reduced benefit of tamoxifen treatment." (PMID 25885472, 2015). "We found that the Aurora kinase B specific inhibitor barasertib preferentially inhibited growth of the fulvestrant resistant T47D breast cancer cell lines compared with growth of the parental fulvestrant sensitive T47D cells." (PMID 25885472, 2015).
breast cancer (continued). "We experimentally validated the expression of FOXM1 and AURKB in 42 breast brain metastasis samples (which included those used in the expression arrays) and in a series of 50 primary breast cancer samples by qRT-PCR." (PMID 24489661, 2014). "Breast cancer cell lines treated with the highly selective AURKB inhibitor Barasertib show anti-neoplastic effects." (PMID 24324792, 2013). "Recent studies reported that Aurora Kinase B expressed abnormally in various malignant tumors, such as breast cancer and acute lymphatic leukemia." (PMID 22809428, 2012). "In summary, these findings demonstrate that acetylation of AURKB at K215 stabilizes c-MYC and may present a key mechanism through which MOF-mediated AURKB acetylation promotes breast cancer cell proliferation." (PMID 40710353, 2025). "Collectively, our findings reveal a novel mechanism by which lysine acetylation regulates AURKB stability, highlight the significance of the MOF-AURKB-c-MYC axis in breast cancer progression, and suggest potential therapeutic strategies targeting this pathway in clinical settings." (PMID 40710353, 2025). "AURKB, as a member of the chromosome passenger complex, is able to phosphorylate chromatin proteins such as histone 3 to aid in mitotic chromosome condensation and is often overexpressed in a wide range of human cancers, including breast cancer." (PMID 40099930, 2025). "In both MCF-7 and MDA-MB-231 breast cancer cells, AURKB depletion led to G2/M phase arrest." (PMID 40710353, 2025). "In conclusion, it has been shown that the let-7b-5p/AURKB axis may be significant in breast cancer progression and the disruption in this axis may contribute to the trigger of Dox resistance." (PMID 39787178, 2025). "To elucidate the molecular mechanism by which MOF-mediated acetylation of AURKB at K215 promotes breast cancer cell proliferation, we first examined the expression levels of key oncogenic proteins, particularly c-MYC, following AURKB knockdown in MCF-7 and MDA-MB-231 cells." (PMID 40710353, 2025). "We also found that AURKB, BIRC5, CDCA8, and FOXM1 are all part of the meta-PCNA proliferation gene signature, and high levels of expression of genes in this signature are associated with poor prognosis in breast cancer." (PMID 39335162, 2024). "In addition, increased AURKB expression in tumor tissues of patients with breast cancer and metastatic colorectal cancer were also found to be significantly associated with reduced survival." (PMID 37318676, 2023). "Collectively, the findings obtained in our study may provide experimental evidence for the involvement of the PRKCE/AURKB/RAB27B axis in the resistance of breast cancer cells to PTX and offer a potential intervention target for reversing tumor drug resistance." (PMID 35088239, 2022). "Our study showed that the let7 family might be regulating AURKB in breast cancer, which needs further exploration." (PMID 34981672, 2022). "Similarly, the AURKB protein was relatively highly expressed in breast cancer tissues, as revealed by immuno-histochemical detection." (PMID 35088239, 2022). "AURKB is overexpressed in Luminal B breast cancers in NHB women." (PMID 36494865, 2022). "In addition, AURKB inhibited the apoptosis of breast cancer cells by promoting Bcl-2 expression and inhibiting Bax expression." (PMID 36561847, 2022). "Subsequent analysis focused on the expression of AURKB in breast cancer cells." (PMID 35088239, 2022). "To further clarify the interaction between DEGs, we screened fifteen hub genes by constructing the PPI network, among which the expression of PSMC6, AURKB, CASP9, BAD, ZNF24, and SSX2IP was associated with OS in breast cancer patients, which attracted our attention." (PMID 36199443, 2022). "However, we know nothing about the specific mechanism by which AURKB phosphorylation influences the drug resistance of breast cancer cells." (PMID 35088239, 2022). "PLK1 and AURKB are more highly overexpressed in basal breast cancers from NHB." (PMID 36494865, 2022).